ACTB (actin beta)
Diseases named in the same sentence as ACTB in open-access papers (continued):
Sharing a sentence is not in itself a finding about the gene and the disease.
tumor (continued). "Up to date, initial evidence shows GAPDH and ACTB are de-regulated in various TNM stages and tumor invasiveness in HCC." (PMID 19200351, 2009). "The analysis showed nearly parallel expression to whole-tissue from the same tumor using the 4-group reference genes for ER+ IBC of TBP, RPLP0, PUM1 and ACTB, as observed by a Pearson correlation of 0.992." (PMID 18211679, 2008). "Moreover, using the TIMER database, we found that the expression of NUBPL and ACTB was closely related to tumor purity, while the correlation of SLC3A2 and DSTN with tumor purity was less pronounced." (PMID 39896807, 2024). "Interestingly, the high abundance identifies were consistent both in the tumor and normal tissues in EESCC and EDAC at the protein level, including HBB, HBA1, HBD, ACTB, ALB, etc.." (PMID 35397555, 2022). "Furthermore, we showed that IL6, CASP3, ACTB, ACTG1 and RAP1B are hub genes that regulate the tumour metastasis regulation network." (PMID 33759378, 2021). "After tumor resection, all of them were tested negative except for one patient whose result was nullified due to his invalid assay value of ACTB internal control." (PMID 33126908, 2020). "ACTB (beta actin) as a housekeeping gene is essential for cell survival, thus it is not surprising that deregulations of ACTB have been described to be involved in curtailing oncogenic processes such as accelerating tumor formation, invasion and metastasis." (PMID 28205611, 2017). "Moreover, the expression levels of ACTB and GAPDH were examined in 80 normal and tumour samples from colorectal, breast, prostate, skin and bladder tissues using qRT-PCR, which revealed that these genes were unsuitable as single reference genes." (PMID 29180379, 2017). "The mRNA for interleukin-8, EGFRvIII and for housekeeping genes such as ACTB, GAPDH were detected in the cargo of TMV and tumour-derived exosomes and shown to be transferred to monocytes, brain microvascular endothelial cells and tumour cells, respectively." (PMID 26626416, 2015). "Conversely, GAPDH and ACTB, the two most commonly reported normalization genes, did not fulfill the criteria of constant expression between normal and tumor samples, as already described by several authors for other malignancies." (PMID 25473950, 2014). "Therefore, we can conclude that for GBM gene expression studies, GUSB along with the most frequently utilized internal controls, ACTB and GAPDH, must be considered inadequate for normalizations due to its significant increase in tumor samples." (PMID 19257903, 2009). "ACTB and GUSB selection, based on geNorm analysis including the seven potential housekeeping genes, probably resulted from similarities in the expression pattern of these two genes, which are both significantly up regulated in tumor tissues, as well as GAPDH." (PMID 19257903, 2009). "First, we measured total cfDNA using a ddPCR assay targeting the ACTB gene, which does not differentiate tumor-derived DNA from non-tumor-derived DNA, potentially introducing confounding factors from non-malignant sources and limiting specificity compared to mutation-specific ctDNA assays." (PMID 41256319, 2025). "Additionally, mRNA levels of ACTB, DSTN, FLNA, and TLN1 increased gradually with the tumor stage." (PMID 37325625, 2023). "In addition, in pathological situations, fusion genes may be formed, such as the ACTB-FOSB and ACTB-GLI1 fusion genes found in some neoplasms." (PMID 34966852, 2021). "To assess the expression level of ANTXR1 in patients with GC, we compared the expression level of ANTXR1 in non-paired tumor and adjacent tissues and paired samples, and the MET was considered as positive control while ACTB was considered as negative control." (PMID 33385012, 2020).
tumor (continued). "Significant expression increase from normal to tumor stomach tissues (p < 0.05) were observed in HPRT1 (p = 0.011) and 18S rRNA (p = 0.021), but not in ACTB (p = 0.058), GAPDH (p = 0.918), B2M (p = 0.740), or RPL29 (p = 0.208)." (PMID 20507635, 2010). "Medium or high expression of IL6, CASP3, ACTB and RAP1B was observed in 14/20 (~70%) lung metastasis tissues and in 11/20 (~55%) tumour tissues, whereas the expression was negative in the majority of adjacent non‐tumour tissues." (PMID 33759378, 2021). "The three most commonly used endogenous controls in protein expression assays, ACTB, TUBB and GAPDH, all displayed significant elevations in tumor samples, indicating that these proteins may not be as reliable as expected." (PMID 27556505, 2016). "RQ by RPL29 (T/N = 2.23×, p = 0.071), HPRT1 (T/N = 1.34×, p = 0.258), ACTB (T/N = 1.60×, p = 0.395), 18S rRNA (T/N = 1.36×, p = 0.527) and RPL29-HPRT1 (T/N = 1.76×, p = 0.086) also showed increasing GPNMB expression in tumor stomach tissues but it was not statistically significant." (PMID 20507635, 2010).
infection (24 papers, 2013 to 2025). The state of being infected such as from the introduction of a foreign agent such as serum, vaccine, antigenic substance or organism. "In the inoculated cultures, WhSBV and cellular ACTB RNA levels were monitored using RT-qPCR over a time period of 240 hours post-infection (hpi)." (PMID 41165328, 2025). "ACTB is essential for cell motility and morphology, significantly influencing the migration of leukocytes to infection sites." (PMID 40243471, 2025). "Increased levels of ACTB arginylation were observed for up to 24 h in Calu-3 cells, with a reduction 48 h after infection." (PMID 36851505, 2023). "We monitored the arginylation levels of one major cytoskeleton protein, ACTB, and observed its increase in the first 2 h after infection in Calu-3 cells, with a decrease at 48 h, when apoptosis-related proteins were activated." (PMID 36851505, 2023). "Viral capsid protein VP1 was probed as a control for infection, and ACTB was probed as a loading control." (PMID 36146840, 2022). "We observed a substantial reduction (greater than 10-fold) in GAPDH and ACTB mRNAs in SARS-CoV-2-infected cells WTACE2 cells as early as 8 h post-infection." (PMID 34315815, 2021). "Last but not least, our results suggest that two reference genes, EF1A and ACTB, are recommended and sufficient for reliable normalization of immune-related genes of tilapia during vaccination and infection." (PMID 25941937, 2015). "Notably, when ACTB expression was altered through siRNA interference or site-directed mutagenesis, the metabolic reprogramming induced by pathogen infection was significantly reversed." (PMID 40867552, 2025). "In addition, D39 infection down-regulated expression of the S phase-specific cell cycle thymidine kinase 1 (TK1) gene and the ACTB gene (~4-fold) encoding β-actin and the ADP-ribosylating factor ARF4 gene (~4-fold)." (PMID 26566142, 2015). "Thus, GAPDH and YWHAZ could be used as reference genes for the normalisation of chicken IEL-NK cell gene response following infection with vvIBDV, whereas the commonly used ACTB is unsuitable to be used as a reference gene in IEL-NK cells infected with vvIBDV." (PMID 32444639, 2020). "Using qRT-PCR, these researchers showed that this reduction was vhs dependent based on two sets of genes that exhibited either high (COL6A2, MMP3, and MMP1) or low (GAPDH, ACTB, and RPLP0) reduction in total RNA levels in WT infection." (PMID 33148793, 2021). "In this study, the expression change of IgM gene was investigated in parallel with six candidate reference genes including 18S rRNA, ACTB, TUBA, UBCE, GAPDH and EF1A during vaccination with vaccine and infection with bacteria in spleen of Nile tilapia." (PMID 25941937, 2015). "In conclusion, RPL30 and SDHA could be used as reference genes for the standardization of in CEF gene response to the infection with ALV-J, whereas commonly used ACTB and GAPDH are unsuitable to be reference genes in ALV-J/CEF settings." (PMID 24099561, 2013). "Based on the importance of the glycolysis–HIF-1α–inflammation axis in infection and M. bovis’s reliance on glycolysis, this study specifically aimed to Identify and characterize the interaction between M. bovis ENO1 and host cell proteins, focusing on ACTB and its critical binding sites." (PMID 40867552, 2025). "After infection or addition of the inhibitor, DNA from three individually infected and 5-AZA treated cultures was extracted and bacterial load was determined using a quantitative real time PCR assay comparing A. phagocytophilum msp2/p44 normalized to a human ACTB standard." (PMID 26225157, 2015). "In this study, we selected six commonly used endogenous controls including 18S rRNA, ACTB, TUBA, UBCE, GAPDH and EF1A as candidate reference genes for normalizing the expression levels of immune-related gene IgM and analyzed their expression stabilities during vaccination and infection in tilapia." (PMID 25941937, 2015).
cardiovascular diseases (5 papers, 2018 to 2025). "The beta-actin gene (ACTB) is implicated in the process of vascular remodeling and further leads to cardiovascular diseases." (PMID 35401927, 2022). "Notably, emerging evidence associates ACTB-encoded β-actin with vascular remodeling—a recognized risk factor for cardiovascular diseases." (PMID 40672380, 2025). "It is also noteworthy that ACTB is differentially expressed in a plethora of cardiovascular diseases, including HCM." (PMID 35401927, 2022). "In addition, some literature also evidenced the differential expressions of ACTB in a variety of cardiovascular diseases." (PMID 39701955, 2024). "Interestingly, a large amount of literature has evidenced the differential expressions of ACTB in a variety of cardiovascular diseases." (PMID 35401927, 2022).
genetic disorder (4 papers, 2022 to 2025). "7p21.1 microdeletion encompassing ACTB is an extremely rare genetic disorder caused by haploinsufficiency of the ACTB gene encoding β-actin, a key cytoskeletal protein involved in cell motility, proliferation, and regulation of gene expression." (PMID 41141068, 2025). "The 7p21.1 microdeletion encompassing ACTB is an extremely rare genetic disorder, with only a limited number of reported cases to date." (PMID 41141068, 2025).
neurodegenerative disease (4 papers, 2020 to 2024). A disorder of the central nervous system characterized by gradual and progressive loss of neural tissue and neurologic function. "HTT, neurofilament heavy chain (NF‐H), Tau (MAPT), FUS, TDP‐43, HNRNPA1, HNRNPD, RPL7 and actin (ACTB, found aggregated in Hirano bodies in several neurodegenerative diseases; Hirano, 1994), were selectively aggregated upon RNase A/T1 treatment of human neuronal lysates." (PMID 32945072, 2020).
neurological disorders (4 papers, 2009 to 2025). "Five known PKA substrates (FLNA, ACTB, SOX9, MAP4K1 and GBF1) interacted with the domain modules of NBEA and three of these are linked with neurological disorders (FLNA, ACTB, SOX9)." (PMID 26999814, 2016).
bacterial infection (2 papers, 2023 to 2025). "Whereas Class2 uniquely included pathways related to bacterial infections (e.g., E. coli, Salmonella) together with actin-cytoskeleton and T-cell modules (e.g., ACTB, PFN1, RAC2, PIK3CD, CD3D/CD3G, STING1, TRADD, CASP8, BCL2, HLA-F)." (PMID 41394852, 2025). "Interestingly, two of the genes that are responsible for the enrichment of bacterial infection (Salmonella, Vibrio cholerae and Escherichia coli) pathways are ACTB and ARF1." (PMID 37243274, 2023).
immune dysfunction (2 papers, 2021 to 2025). "Here, we characterize immune dysfunction associated with a novel ACTB variant in a patient with BRWS1." (PMID 40748410, 2025).
infectious disease (2 papers, 2014 to 2015). A disorder directly resulting from the presence and activity of a microbial, viral, or parasitic agent in humans. "Analysis of the biofunctions related with diseases and disorders showed that these proteins are included in neurological (p = 5.8E-04–1.2E-02) and infectious diseases (CHMP.5 and ACTB) (p = 8.5E-03 – 8.5E-03)." (PMID 26152126, 2015).
kidney disease (2 papers, 2021 to 2023). "This supports the proposal that the blood-based ACTB hypo-malonylation may serve as a potential biomarker to help in the development of kidney disease." (PMID 37833721, 2023).
benign tumors (1 paper, 2020). "The median DNA methylation levels that were normalized by ACTB were 0.0098 in CRC tumors, 0.0015 in benign tumors, and 0.0001 in adjacent normal tissues." (PMID 32398064, 2020).
congenital malformation syndrome (1 paper, 2017). "β-actin is encoded by ACTB, and pathogenic variations in this gene have typically been associated with Baraitser-Winter cerebrofrontofacial syndrome (BRWS; OMIM 243310), a congenital malformation syndrome typified by short stature, craniofacial anomalies, and cerebral anomalies." (PMID 28487785, 2017).
hematological cancers (1 paper, 2020). "In addition, when compared to the frequency of ACTB mutation in hematological cancers the frequency of RHOA mutations follows an analogous pattern." (PMID 32349449, 2020).
ACTB also shares sentences with these, for which no sentence is quoted: neurodevelopmental disorder (5 papers); Baraitser-Winter syndrome 1 (4); coloboma (3); diffuse large B-cell lymphoma (3); lung adenocarcinoma (3); major depression (3); renal cell carcinoma (3); Salmonella Infections (3); acute lymphoblastic leukemia (2); amyotrophic lateral sclerosis (2); colon adenocarcinoma (2); colorectal tumor (2); disc degeneration (2); esophageal squamous cell carcinoma (2); heart failure (2); hematological malignancies (2); Hodgkins lymphoma (2); malaria (2); medulloblastoma (2); metastatic melanoma (2); osteogenesis imperfecta (2); scoliosis (2); soft tissue tumor (2); stomach cancer (2); acute myeloid leukemia (1); adenocarcinoma (1); Allergy (1); anemia (1); arrhythmogenic right ventricular cardiomyopathy (1); Arthritis (1).
A further 83 diseases each share a sentence with ACTB in 1 paper.